NKD1 (NKD inhibitor of Wnt signaling pathway 1)
Diseases named in the same sentence as NKD1 in open-access papers (continued):
Sharing a sentence is not in itself a finding about the gene and the disease.
hepatocellular carcinoma (7 papers, 2017 to 2025). A malignant tumor that arises from hepatocytes. "Researchers have reported that NKD1 expression is low in breast cancer, osteosarcoma, acute myeloid leukemia, hepatocellular carcinoma, and non-small-cell lung cancer tissues." (PMID 40675969, 2025). "Researchers have reported that NKD1 is expressed at low levels in breast cancer tissues, hepatocellular carcinoma, and acute myeloid leukemia; However, it is also highly expressed in colorectal, gastric and pancreatic cancer cells." (PMID 40675969, 2025). "For example, Arend Koch and his colleagues observed an elevated level of NKD1 in hepatoblastoma although low NKD1 expression was observed in hepatocellular carcinoma." (PMID 36969985, 2023). "For instance, HNF1A-AS1 promotes hepatocellular carcinoma cell proliferation by repressing the NKD1 and p21 expression via interacting with EZH2, or by sponging miR-30b-5p to promote autophagy." (PMID 33024199, 2020). "This gene inhibits hepatocellular carcinoma by regulating PHF19, regulates rectal cancer through CDK8, regulates osteosarcoma by inhibiting NKD1, regulates prostate cancer through Fra-1 or RPS6KB1." (PMID 28498798, 2017). "Interestingly, one of the Wnt antagonists included in the previous study, NKD1, was shown to be directly regulated by the PRC2 complex in hepatocellular carcinoma." (PMID 30119689, 2018).
adenoma (4 papers, 2008 to 2023). A neoplasm arising from the epithelium. "Differential gene expression analysis of the scRNA-seq data from the adenoma cells showed substantially fewer transcripts encoding the Wnt antagonists Axin2, Dkk2, Dkk3, Wif1, Notum, and Nkd1 in the LApcL mice than in the LApc mice." (PMID 34788095, 2021). "A reduction in NKD1 expression was observed in two FAP adenomas (2a and 6a) compared with their matched normal tissue." (PMID 20628379, 2010). "NKD1 expression was up-regulated (>4-fold) in 19 out of 26 FAP adenomas and all 9 sporadic adenomas." (PMID 20628379, 2010). "The inter-quartile ranges of FZD3 induction in the sporadic and FAP adenoma groups (3–17 vs 1.0–26) showed much greater similarity than a similar comparison for NKD1 (79–1053 vs 2–62)." (PMID 20628379, 2010). "Adenomas from these patients had also been analysed for mRNA expression of β-catenin transcription target genes (sFRP1, NKD1 and c-myc) and the FZD3 receptor." (PMID 20628379, 2010). "Transcription of the Wnt/planar cell polarity pathway determinant NKD1 (naked cuticle homologue 1) was induced in adenomas by a median 135-fold and in cancers by 7.4-fold." (PMID 18414471, 2008). "The median level of NKD1 induction in cancers (7.4-fold) was substantially lower than the 135-fold we saw in adenomas." (PMID 18414471, 2008). "As adenomas progress into cancers, NKD1 expression reduces and its relationship with FZDs3 and 6 levels is lost." (PMID 18414471, 2008). "Performing these experiments for NKD1 revealed substantial induction in all but 2 of 14 adenomas, compared with normal mucosa." (PMID 18414471, 2008). "We devised conventional RT–PCR assays for NKD1 and each of the human FZD sequences and used these to analyse RNA extracted from a series of adenomas and control normal mucosa samples." (PMID 18414471, 2008). "For instance in adenomas 2a and 6a sFRP1 and NKD1 are both down-regulated and in adenoma 8a sFRP1 is down-regulated but there is no change in NKD1 expression." (PMID 20628379, 2010). "In sporadic adenomas the down-regulation of sFRP1 correlates directly with an up-regulation of NKD1, but this is not always the case in the FAP adenomas." (PMID 20628379, 2010). "In cultured cells, stabilisation of β-catenin using lithium treatment led to NKD1 expression but failed to influence Wnt/Ca2+ receptors, while Wnt growth factor treatment induced FZD3 transcripts to the degree seen in adenomas." (PMID 18414471, 2008). "In addition, there was no clear relationship between NKD1 and FZD3 induction, contrasting with the expression profiles seen in adenomas." (PMID 18414471, 2008).
colorectal adenoma (4 papers, 2008 to 2023). An adenoma that arises from the colon or rectum. "For instance, NKD1 is upregulated in hepatoblastoma and colorectal adenomas whereas NKD1 is downregulated in breast cancer, lung adenocarcinoma, non-small cell lung cancer, and acute myeloid leukemia." (PMID 37857014, 2023). "It has been reported that the NKD1 mRNA level was up-regulated in colorectal adenomas and hepatoblastoma." (PMID 21599923, 2011). "Since the qualitative review of expression indicated induction of NKD1, FZD3 and FZD6 in colorectal adenomas, we developed quantitative real-time RT–PCR assays for each of these to determine the extent of the induction." (PMID 18414471, 2008). "In this paper, we show that NKD1, FZD3 and FZD6 transcripts are all induced significantly in colorectal adenomas compared to matched normal tissue, indicating that both the Wnt/PCP and the Wnt/Ca2+-response pathways are expressed at an early stage in tumour formation." (PMID 18414471, 2008). "Using real-time PCR, we found that the expression of downstream transcriptional targets of the β-catenin/TCF signaling pathway that are known to be elevated in colorectal adenoma and carcinomas, such as AXIN2, NKD1, and IRS1, were not decreased by RAP treatment in the HCECs." (PMID 24763434, 2014).
glioblastoma (4 papers, 2018 to 2023). The most malignant astrocytic tumor (WHO grade IV). "Of note, the promoter region of NKD1 and those of other genes encoding for Wnt inhibitors are frequently hypermethylated in glioblastoma, where their expression is consequently very low." (PMID 29643989, 2018). "Here, we aimed to investigate expression and function of NKD inhibitor of Wnt signaling pathway 1 (NKD1), an antagonist of Wnt-beta-catenin signaling pathways, in glioblastoma." (PMID 36969985, 2023). "Two glioblastoma cell lines, U87 and U251, were used to further investigate the tumor-related role of NKD1 through overexpression strategy in combination with cell proliferation assays." (PMID 36969985, 2023). "NKD1 shows a lower expression level in glioblastoma compared to that in the normal brain or other glioma subtypes, which is independently correlated to a worse prognosis in both the TCGA cohort and our retrospective cohort." (PMID 36969985, 2023). "Immune cell enrichment in glioblastoma and its correlation with NKD1 level was finally assessed using bioinformatics analyses." (PMID 36969985, 2023). "All this data, together with the recognized role of the Wnt pathway in glioblastoma, suggests a possible importance of NKD1 repression in glioblastoma oncogenesis." (PMID 29643989, 2018). "Overexpressing NKD1 in glioblastoma cell lines can significantly attenuate cell proliferation." (PMID 36969985, 2023). "NKD1 inhibits glioblastoma progression and its downregulated expression indicates a poor prognosis." (PMID 36969985, 2023). "We found a further confirmation that H3K27 trimethylation is a common feature contributing to the repressed state of NKD1 not only in cell lines but also in glioblastoma tissues, by data mining in The Canadian Epigenetics, Epigenomics, Environment and Health Research Consortium (CEEHRC)." (PMID 29643989, 2018). "We now show for the first time that H19 can regulate NKD1 expression in glioblastoma cells, and we suggest that NKD1 inhibition may be one of the ways through which H19 participates to glioblastoma growth." (PMID 29643989, 2018). "In our recent work, where we compared gene expression in glioblastoma tissues to peritumoral regions of the same patients, we observed that, while H19 was clearly overexpressed in tumors, the opposite was true for NKD1 (Log2FC peri vs tumor = 1.22, p = 0.0086)." (PMID 29643989, 2018). "Upon knock-down of H19 both cell lines showed an increase in Nkd1 expression, at the mRNA as well as at the protein level, suggesting that this lncRNA might affect Nkd1 expression in glioblastoma cells." (PMID 29643989, 2018). "In addition, expression of NKD1 in glioblastoma is negatively correlated to the T cell infiltration, indicating it may have crosstalk with the tumor immune microenvironment." (PMID 36969985, 2023). "Finally, the potential tumorigenicity of glioblastoma cells may also be affected by recruitment of EZH2 (a subunit of the Polycomb Repressive Complex 2) to the NKD1 promoter by H19, with its repression positively contributing to glioblastoma tumorigenicity." (PMID 32283739, 2020). "Even more directly related to our findings is the observation by Lin B. and colleagues who, by studying H3K4me3 and H3K27me3 profiles in 8 glioblastoma stem cell lines, found that NKD1 promoter contains H3K27me3 marks in 5/8 GBM stem cell lines." (PMID 29643989, 2018). "H19 binds EZH2 in glioblastoma cells, and that EZH2 binding to NKD1 and other promoters is impaired by H19 silencing." (PMID 34296520, 2021). "More specifically, we demonstrated that the depletion of H19 in glioblastoma cells is translated into a specific reduction of EZH2 binding and H3K27 trimethylation at the NKD1 promoter, with a consequent increase of Nkd1 levels." (PMID 29643989, 2018). "Indeed, we showed that H19 binds EZH2 in glioblastoma cells, and that EZH2 binding to NKD1 and other promoters is impaired by H19 silencing." (PMID 29643989, 2018).
breast carcinoma (3 papers, 2015 to 2025). "NKD1 was unmethylated in 6 normal breast tissue samples and 68 cases of human primary breast cancer samples." (PMID 26124080, 2015). "The expression of NKD1 and NKD2 was regulated by promoter region methylation in breast cancer cells." (PMID 26124080, 2015). "As NKD1 methylation did not appear to be a major event in human breast cancer, we mainly focused on the mechanisms of NKD2 in breast carcinogenesis." (PMID 26124080, 2015). "No NKD1 methylation was found in primary human breast cancer." (PMID 26124080, 2015). "The results demonstrate that NKD1 may not play an important role in breast cancer and progression." (PMID 26124080, 2015).
lung carcinoma (3 papers, 2011 to 2025). "We found that NKD1 protein was down-regulated in lung cancer tissues, which was associated with poor differentiation, high pTNM stage, lymph node metastasis and poor prognosis of NSCLC." (PMID 21599923, 2011). "In 35 fresh lung cancer tissues examined, 27(79%) of them exhibited lower levels of NKD1 protein in comparison with their corresponding normal tissue (P = 0.009)." (PMID 21599923, 2011). "Thereby, the NKD1 protein tends to beat a low level in lung cancer cells, even though the classical Wnt pathway is constantly shown to be activated." (PMID 21599923, 2011). "In order to examine the effect of NKD1 on the invasiveness of lung cancer cells, we down-regulated NKD1 expression in the LTEP and LK cell lines and evaluated the change of their invasive abilities by the Matrigel invasion assay." (PMID 21599923, 2011). "The results showed that the NKD1 protein expression in HBE was higher than in the lung cancer cell lines." (PMID 21599923, 2011). "Since Dvl-1 and β-catenin function as positive regulators of the canonical Wnt signaling pathway, it is plausible that NKD1 may increase the invasive ability of lung cancer cells through activating the canonical Wnt pathway." (PMID 21599923, 2011). "The result further indicated that NKD1 might play a role as a negative regulator of the canonical Wnt signaling pathway in these two lung cancer cell lines." (PMID 21599923, 2011). "Compared with normal tissues, the expression of ADM2, CLIC6, KIF20A, LAD1, MUC5B, and TNS4 was up-regulated, and the expression of ATG16L2, KCNK3, MAFF, NKD1, and SPATA13 was down-regulated in lung cancer tissues." (PMID 34804921, 2021). "Furthermore, our NKD1 knockdown assays using the siRNA technology revealed an enhanced invasive ability in LTEP and LK cells, supporting the notion that loss of NKD1 activity might critically contribute to the metastatic potential in lung cancer cells." (PMID 21599923, 2011). "In addition, NKD1 knockdown could up-regulate Dishevelled-1 and β-catenin protein levels, as well as increased MMP-7 transcription and the invasive ability of lung cancer cells." (PMID 21599923, 2011). "In addition, NKD1 knockdown by siRNA technology could markedly up-regulate Dishevelled-1 and β-catenin protein levels, enhance the transcription of MMP-7 and promote the invasiveness of lung cancer cells." (PMID 21599923, 2011). "To test this hypothesis, we examined the expression of MMP-7(a target gene of the canonical Wnt pathway) in NKD1-depleted cells and found that MMP-7 mRNA levels were significantly increased in comparison with lung cancer cells without NKD1 depletion (P < 0.05)." (PMID 21599923, 2011).
non-small cell lung carcinoma (3 papers, 2011 to 2025). A group of at least three distinct histological types of lung cancer, including non-small cell squamous cell carcinoma, adenocarcinoma, and large cell carcinoma. "However, the expression pattern and clinicopathological significance of NKD1 in patients with non-small-cell lung cancer (NSCLC) is still unclear." (PMID 21599923, 2011).
bladder cancer (2 papers, 2018 to 2020). "In bladder cancer, H19 was shown to direct EZH2 to the promoter region of Nkd1, thus inducing the trimethylation of H3K27 and the consequent repression of transcriptional activity." (PMID 29643989, 2018).
colorectal tumor (2 papers, 2016 to 2021). "Three R288H mutations in Nkd1 were detected in a colorectal tumor and 2 renal tumors." (PMID 27007149, 2016).
glioma (2 papers, 2018 to 2023). A benign or malignant brain and spinal cord tumor that arises from glial cells (astrocytes, oligodendrocytes, ependymal cells). "Interestingly, the NKD1-mRNA level was significantly lower in gliomas with wild type IDH than those with mutated IDH (P < 0.001)." (PMID 36969985, 2023). "As expected, low NKD1 is significantly correlated with worse overall survival, cancer-specific survival, and progress-free survival of glioma (all P < 0.001)." (PMID 36969985, 2023). "The mRNA level of NKD1 was firstly retrieved from TCGA glioma dataset to evaluate its correlation with clinical characteristics and its value in prognosis prediction." (PMID 36969985, 2023). "Consistently, by dividing patients based on the WHO grade, we found that Grade IV GBM showed significantly a lower NKD1-mRNA level than Grade II or Grade III gliomas (P < 0.001)." (PMID 36969985, 2023). "NKD1 shows a decreased expression level in GBMs compared to normal brains or other glioma types, and its low expression results in poor GBM prognosis via enhancing GBM progression." (PMID 36969985, 2023). "Therein, where H3K27me3 ChIP-seq data from 5 glioma patients’ tissues are deposited, we found that the regulatory region of NKD1 indeed contains peaks of H3K27 trimethylation." (PMID 29643989, 2018). "We firstly analyzed the mRNA level of NKD1 in glioma tissues from the TCGA dataset." (PMID 36969985, 2023). "Thirdly, recent studies suggested that NKD1 could serve as an independent predicting biomarker for tumor responsiveness of neoadjuvant chemo-radiotherapy in rectal cancer, and whether NKD1 can help direct chemotherapy of gliomas deserve further investigations." (PMID 36969985, 2023). "In other words, lower-NKD1 mRNA level may predict poor glioma prognosis." (PMID 36969985, 2023). "It has been well-recognized that gliomas with 1p/19q codeletion possess better prognosis than those with noncodeletion, therefore, we next compared whether NKD1-mRNA show any expression difference in those two types." (PMID 36969985, 2023).
melanoma (2 papers, 2017 to 2022). A malignant, usually aggressive tumor composed of atypical, neoplastic melanocytes. "Moreover, the use of an anti-NKG2D blocking mAb strongly decreased NK92-, NKd1- and NKd2-mediated killing of T1 melanoma cells, demonstrating that NKG2D is an important determinant for the lysis of T1 cells by NK cells." (PMID 28423623, 2017). "Similar results were also obtained using the melanoma tumor cell line WM17-16 and NKd1 effector cells." (PMID 28423623, 2017).
prostate carcinoma (2 papers, 2017). A carcinoma that arises from epithelial cells of the prostate gland. "Altogether, above results clearly indicate that miR-744 activates Wnt/β-catenin pathway by targeting multiple negative regulators and NKD1 is a main functional target of miR-744 in prostate cancer development." (PMID 28107193, 2017). "Thus, above experiments demonstrated that NKD1 is a critical downstream mediator of miR-744 effects in prostate cancer progression." (PMID 28107193, 2017).
astrocytoma (1 paper, 2023). "Accordingly, astrocytoma, oligoastrocytoma, and oligodendroglioma showed similar NKD1-mRNA level without statistically significant difference." (PMID 36969985, 2023).
coloboma (1 paper, 2018). An abnormality in which a part of a structure in one or both eyes is missing. "In examining the prioritized list of rare variants identified in superior coloboma patients, we note rare variants in NKD1, CELSR2, FZD4, SCRIB, and WNT9B (components of canonical or non-canonical Wnt pathways)." (PMID 29522511, 2018).
colorectal adenocarcinoma (1 paper, 2009). The most common type of colorectal carcinoma. "Our data raise the hypothesis that specific NKD1 mutations promote Wnt-dependent tumorigenesis in a subset of DNA mismatch-repair-deficient colorectal adenocarcinomas and possibly other Wnt-signal driven human cancers." (PMID 19956716, 2009).
Ewing sarcoma (1 paper, 2019). A small round cell tumor that lacks morphologic, immunohistochemical, and electron microscopic evidence of neuroectodermal differentiation. "In this study, we showed that APCDD1 knockdown increased the expression of CDC25A, LRP6, LEF1 and NKD1, which are confirmed targets of the canonical Wnt pathway in Ewing sarcoma, implying that APCDD1 might act as a Wnt inhibitor in this cancer." (PMID 30496486, 2019).
leiomyoma (1 paper, 2023). A well-circumscribed benign smooth muscle neoplasm characterized by the presence of spindle cells with cigar-shaped nuclei, interlacing fascicles, and a whorled pattern. "Others have also reported overexpression of WIF1 and other WNT-protein inhibitors such as SFRP1, FBXW11, NKD1, and SFPR4 in leiomyomas." (PMID 36835153, 2023).
liver cancer (1 paper, 2025). An epithelial or non-epithelial malignant neoplasm that arises from the liver. "However, the protein expression level of NKD1 is low in gastric and liver cancer cells, and the expression of NKD1 inhibits the expression of β-catenin." (PMID 40675969, 2025). "Therefore, in gastric and liver cancer cells with low NKD1 expression, β-catenin gene expression is significantly negatively correlated with that of NKD1." (PMID 40675969, 2025).
lymph node metastasis (1 paper, 2011). "Our immunohistochemical results demonstrated that reduced NKD1 expression was associated with poor differentiation, high pTNM stage, lymph node metastasis and poor prognosis in NSCLC." (PMID 21599923, 2011). "The reduced NKD1 expression was correlated with histological type (P = 0.003), poor differentiation (P = 0.004), lymph node metastasis (P = 0.013), TNM stage (P = 0.002) and poor survival (62.88 ± 3.23 versus 23.61 ± 2.18 months, P = 0.03)." (PMID 21599923, 2011).
ovarian tumors (1 paper, 2024). "When BRCA2mt ovarian tumors were compared with BRCA1mt tumors, eight genes (NOTUM, SFRP5, RNF43, ZNRF3, DKK1, DKK4, NKD1, and AXIN2) that negatively regulate Wnt signaling were upregulated in BRCA2mt tumors." (PMID 39028933, 2024).